CHMP2B (charged multivesicular body protein 2B)
Description:
Probable core component of the endosomal sorting required for transport complex III (ESCRT-III) which is involved in multivesicular bodies (MVBs) formation and sorting of endosomal cargo proteins into MVBs. MVBs contain intraluminal vesicles (ILVs) that are generated by invagination and scission from the limiting membrane of the endosome and mostly are delivered to lysosomes enabling degradation of membrane proteins, such as stimulated growth factor receptors, lysosomal enzymes and lipids. The MVB pathway appears to require the sequential function of ESCRT-O, -I,-II and -III complexes. ESCRT-III proteins mostly dissociate from the invaginating membrane before the ILV is released. The ESCRT machinery also functions in topologically equivalent membrane fission events, such as the terminal stages of cytokinesis and the budding of enveloped viruses (HIV-1 and other lentiviruses). ESCRT-III proteins are believed to mediate the necessary vesicle extrusion and/or membrane fission activities, possibly in conjunction with the AAA ATPase VPS4.
Synonyms: Vps2-2; DKFZP564O123; CHMP2.5; VPS2B; ALS17; DMT1; FTDALS7
Tractability: Antibody: UniProt places it where antibodies can reach, with high confidence; its Gene Ontology location is reachable by antibodies, with high confidence. PROTAC: ubiquitination databases record sites on it; its protein half-life has been measured.
Gene: Protein-coding gene on chromosome 3 (87,227,271 to 87,255,556, forward strand). Ensembl gene ENSG00000083937.
Subcellular location: Cytoplasm, cytosol; Late endosome membrane
Subcellular location (Human Protein Atlas): Cytosol
Pathways (Reactome):
Disease: Budding and maturation of HIV virion; HCMV Late Events; Translation of Replicase and Assembly of the Replication Transcription Complex
Autophagy: Late endosomal microautophagy; Macroautophagy
Cell Cycle: Sealing of the nuclear envelope (NE) by ESCRT-III
Programmed Cell Death: Pyroptosis
Vesicle-mediated transport: Endosomal Sorting Complex Required For Transport (ESCRT)
Gene Ontology:
Molecular function: cadherin binding; protein binding; protein domain specific binding
Biological process: autophagosome maturation; autophagy; cognition; endosome organization; late endosome to lysosome transport; midbody abscission; mitotic metaphase chromosome alignment; multivesicular body sorting pathway; neuron cellular homeostasis; nuclear membrane reassembly; nucleus organization; plasma membrane repair; regulation of centrosome duplication; regulation of mitotic spindle assembly; ubiquitin-dependent protein catabolic process via the multivesicular body sorting pathway; viral budding from plasma membrane; viral budding via host ESCRT complex; viral release from host cell; ESCRT III complex disassembly; late endosome to vacuole transport; macroautophagy; membrane fission; multivesicular body assembly; multivesicular body-lysosome fusion; vesicle fusion with vacuole; and 1 more
Cellular component: amphisome membrane; autophagosome membrane; cytoplasm; cytosol; endosome; ESCRT III complex; extracellular exosome; kinetochore; kinetochore microtubule; late endosome; lysosomal membrane; lysosome; midbody; multivesicular body membrane; nuclear pore; plasma membrane; late endosome membrane
Genetic constraint (gnomAD): Loss-of-function variants: 10 observed, 11.22 expected, observed/expected ratio (o/e) 0.89, 90% interval 0.55 to 1.5. The upper end of that interval is the gene's LOEUF score, 1.5, which puts it in group 6 of 6, group 1 being the genes least tolerant of losing a copy. Missense variants: 132 observed, 130.76 expected, observed/expected ratio (o/e) 1.01, 90% interval 0.88 to 1.17. Synonymous variants: 42 observed, 42.49 expected, observed/expected ratio (o/e) 0.99, 90% interval 0.77 to 1.28.
Gene-disease validity (ClinGen):
ClinGen rates the evidence that CHMP2B causes each of these diseases.
frontotemporal dementia and/or amyotrophic lateral sclerosis 7 (autosomal dominant): Definitive.
Homologues: Orthologues: chimpanzee CHMP2B (100% identical), dog CHMP2B (99% identical), mouse Chmp2b (99% identical), guinea pig CHMP2B (98% identical), macaque CHMP2B (95% identical), rat Chmp2b (95% identical), pig CHMP2B (94% identical), tropical clawed frog chmp2b (88% identical), zebrafish chmp2bb (84% identical), rabbit CHMP2B (83% identical), zebrafish chmp2ba (82% identical), Drosophila melanogaster CHMP2B (47% identical), and 1 more. Paralogues in human: CHMP2A (34% identical), CHMP3 (27% identical), CHMP1B (16% identical), CHMP1A (15% identical).
Diseases named in the same sentence as CHMP2B in open-access papers:
CHMP2B is named in the same sentence as 64 diseases in open-access papers, as found by Europe PMC text mining. Sharing a sentence is not in itself a finding about the gene and the disease. The quoted sentences say what the papers report.
frontotemporal dementia (59 papers, 2008 to 2025). Frontotemporal dementia (FTD) comprises a group of neurodegenerative disorders, characterized by progressive changes in behavior, executive dysfunction and language impairment, as a result of degeneration of the medial prefrontal and frontoinsular cortices. "This study investigates the axonal trafficking of the ESCRT-III protein CHMP2b and shows how the frontotemporal dementia–causative CHMP2bintron5 mutation disrupts its transport and synaptic localization." (PMID 40021219, 2025). "For this present study, we elected to focus on the role of CHMP2B given that mutations in CHMP2B have been implicated in Frontotemporal Dementia (FTD) and a lower motor neuron predominant form of ALS." (PMID 39709457, 2024). "The use of skin fibroblasts from FTD3 (Frontotemporal Dementia with CHMP2B mutations) patients offers a valuable approach for creating patient-specific models of the disease." (PMID 39766775, 2024). "CHMP2B mutation was associated with neurodegeneration in frontotemporal dementia (FTD) and amyotrophic lateral sclerosis (ALS)." (PMID 36330465, 2022). "Chromosome 3-linked frontotemporal dementia (FTD3) is caused by a gain-of-function mutation in CHMP2B, resulting in the production of a truncated toxic protein, CHMP2BIntron5." (PMID 36414997, 2022). "Mutations in CHMP2B (Vps2 homolog) were identified in some patients with FTD (frontotemporal dementia) and in ALS (amyotrophic lateral sclerosis)." (PMID 30809208, 2019). "Frontotemporal dementia linked to chromosome 3 (FTD3) is a rare heterozygous early-onset form of frontotemporal dementia, which is caused by a point mutation in the gene encoding the charged multivesicular protein 2B (CHMP2B) located to the human chromosome 3." (PMID 32435294, 2019). "Mutations in the endosome-associated protein CHMP2B cause frontotemporal dementia and lead to lysosomal storage pathology in neurons." (PMID 30496365, 2018). "Frontotemporal dementia (FTD)-causing mutations in the CHMP2B gene lead to the generation of mutant C-terminally truncated CHMP2B." (PMID 28093491, 2017). "CHMP2B, linked genetically to frontotemporal dementia (FTD) and AD, directly interacts with and recruits the VPS4 AAA–ATPase complex that disassembles ESCRT-III, and genome-wide association studies for late onset AD identified an association with VPS4B." (PMID 28835279, 2017). "The genes for four proteins involved in this process (TDP43, FUS, VCP, and CHMP2B) have mutations in various familial cases of the neurodegenerative diseases fronto-temporal dementia (FTD) or amyotrophic lateral sclerosis (ALS)." (PMID 27242399, 2016). "Mutations in the charged multivesicular body protein 2B (CHMP2B) cause frontotemporal dementia (FTD)." (PMID 26358247, 2015). "Mutations in the Endosomal Sorting Complex Required for Transport- (ESCRT-) III subunit CHMP2B are associated with FTD (frontotemporal dementia) and ALS (amyotrophic lateral sclerosis)." (PMID 24949430, 2014). "Rare cases of frontotemporal dementia as well as motor neuron diseases are caused by mutations in the ESCRT-III protein CHMP2B." (PMID 23829673, 2013). "Chmp2b mutations have been observed in Danish, Belgian, Dutch, American, and French patients with frontotemporal dementia (FTD)." (PMID 23284619, 2012). "The first mutation in CHMP2B was identified in frontotemporal dementia linked to chromosome 3 (FTD-3), an autosomal dominant FTD which occurs in one large kindred from Denmark." (PMID 21222599, 2011). "Mutations in the ESCRT‐III subunit CHMP2B (charged multivesicular body protein 2B)—required to sort integral membrane proteins into intraluminal vesicles of the multivesicular body (MVB)—have been causally linked to frontotemporal dementia and ALS." (PMID 34459017, 2021).
frontotemporal dementia (continued). "Among the ESCRT-III components, mutations in the Chmp2B gene are reported to be associated with frontotemporal dementia (FTD) and amyotrophic lateral sclerosis (ALS), which provides a clear link between dysfunction in the ESCRT-III machinery and neurodegeneration." (PMID 34625123, 2021). "Furthermore, mutations in CHMP2B, part of a complex involved in endosome-lysosome fusion, cause frontotemporal dementia." (PMID 32938453, 2020). "Mutations in the endosome-associated protein CHMP2B cause frontotemporal dementia (FTD)." (PMID 30496365, 2018). "Mutations in the gene encoding the ESCRT-III component charged multivesicular body protein 2B (CHMP2B) are associated with frontotemporal dementia (FTD), FTD with motor neuron disease, and amyotrophic lateral sclerosis (ALS)." (PMID 40563427, 2025). "A rare cause of inherited frontotemporal dementia (FTD) is a mutation in the CHMP2B gene on chromosome 3 leading to the autosomal dominantly inherited FTD (CHMP2B-FTD)." (PMID 34588974, 2021). "Another study showed that overexpression of mutant CHMP2B, which is associated with Frontotemporal dementia (FTD), in primary cortical neurons increased dendritic branches and decreased endolysosomal trafficking in dendrites." (PMID 33192307, 2020). "The best studied example is frontotemporal dementia linked to chromosome 3 (FTD-3) which occurs in a large Danish family, with a further CHMP2B mutation identified in an unrelated Belgian familial FTD patient." (PMID 21222599, 2011). "Additionally, rare mutations in the endosomal-lysosomal gene CHMP2B—linked to frontotemporal dementia (FTD) but with overlapping AD pathology—disrupt autophagosome maturation, further underscoring the centrality of lysosomal clearance in AD." (PMID 40940752, 2025). "In frontotemporal lobar degeneration, Neary, David works on issues such as genetics, which are connected to tau protein and charged multivesicular body protein 2B." (PMID 39087008, 2024). "Here, we provide molecular and functional evidence of major changes in neuronal energy metabolism in CHMP2B mediated Frontotemporal Dementia (FTD3) using patient-derived iPSC disease models." (PMID 32928252, 2020). "In addition, mutated CHMP2B (component of ESCRT-III) leads to Frontotemporal dementia linked to chromosome 3 (FTD-3) because of autophagosome and ubiquitinated protein accumulation." (PMID 30726272, 2019). "A mutation in CHMP2B, a subunit of the endosomal sorting complex required for transport-III (ESCRT-III), causes an autosomal dominant form of frontotemporal dementia (FTD) in a Danish cohort." (PMID 30496365, 2018). "Three of these variants have been described in patients with AD, PD or frontotemporal lobar degeneration and amyotrophic lateral sclerosis (Patient A:PSEN2 p.D439A;16, 17 B:CHMP2B p.I29V;18 and C:SQSTM1 p.A33V,19, 20)." (PMID 26836416, 2016). "For example, mutations in the charged multivesicular body protein 2B (CHMP2B), an ESCRT-III subunit, were identified in familial cases of frontotemporal dementia (FTD) and ALS11." (PMID 27112194, 2016). "Mutations in charged multivesicular body protein 2B (CHMP2B), which is involved in endosomal protein trafficking, have been found in chromosome 3-linked frontotemporal dementia." (PMID 26651479, 2015). "mSnf7-2 also binds to CHMP2B, an ESCRT-III subunit for which mutations have been found to cause a rare form of Frontotemporal Dementia, as discussed in the next section." (PMID 23829673, 2013). "CHMP2B mutations are a rare cause of autosomal dominant frontotemporal dementia (FTD)." (PMID 21222599, 2011). "Recently, we identified missense mutations in CHMP2B (charged multivesicular protein 2B) in two individuals with familial ALS, one of whom had associated features of frontotemporal dementia (FTD)." (PMID 20352044, 2010).
frontotemporal dementia (continued). "In this regard, Parkinson’s Disease is commonly associated with endolysosomal trafficking phenotypes, while CHMP2B and CHMP1B, whose homologues both play roles in Rab11-exosome and DCG biogenesis in fly SCs, are linked to frontotemporal dementia and hereditary spastic paraplegia respectively." (PMID 40676215, 2025). "The research on CHMP2B is mainly focused on autophagy, frontotemporal dementia and amyotrophic lateral sclerosis, suggesting that CHMP2B could be one of the targets through which CCT2 participated in autophagy and affecting the course of AMD." (PMID 40374738, 2025). "For example, charged MVB protein 2B (CHMP2B) is a subunit of ESCRT and mutation of CHMP2B could lead to the pathogenesis of amyotrophic lateral sclerosis and frontotemporal dementia." (PMID 37122628, 2023). "Indeed, mutations in CHMP2B, a gene encoding one of the four major proteins of ESCRT-III complex, can cause frontotemporal dementia (FTD), ALS or FTD-ALS." (PMID 34359848, 2021). "For example, several genes causing ALS and/or frontotemporal dementia (C9orf72, VCP, SQSTM1, OPTN, UBQLN2, GRN, CHMP2B) affect the autophagic machinery; and some Alzheimer’s Disease genes (APOE, TREM2, CD33, ABCA7) are preferentially or exclusively expressed in microglia." (PMID 33892821, 2021). "Additionally, variants of CHMP2B, a component of the ESCRT machinery that functions in multivesicular body formation, are associated with frontotemporal dementia." (PMID 26692002, 2015). "Amongst these other genes, CHMP2B was the first gene associated with both ALS and frontotemporal dementia (FTD) showing for the first time a genetic link between these two neurodegenerative diseases." (PMID 35454086, 2022). "Mutations in CHMP2B are an uncommon cause of amyotrophic lateral sclerosis (ALS) and frontotemporal dementia (FTD), two neurodegenerative diseases with clinical, genetic, and pathological overlap." (PMID 35454086, 2022). "Mutations in CHMP2B, an ESCRT‐III (endosomal sorting complexes required for transport) component, are associated with frontotemporal dementia (FTD) and amyotrophic lateral sclerosis (ALS)." (PMID 32123847, 2019). "None of these CHMP2B mutations was present in our control subjects; however, in one control subject (0.13%) we did detect a mutation (p.S194L [c.581C>T]) that had previously been reported in a patient with frontotemporal dementia (FTD)." (PMID 23155438, 2012). "Staining of tissue from Alzheimer disease patients with CHMP2B showed an accumulation of the protein in vesicular structures resembling Granulo Vacuolar Degeneration suggestive of a defective autophagic and late endocytic pathways in AD and Frontotemporal lobar degeneration." (PMID 22783199, 2012). "Likewise, UDCA was found to convey neuroprotection in drosophila and mammalian models of charged multivesicular body protein 2B (CHMP2B) Intron 5 (CHMP2BIntron5) induced frontotemporal dementia (FTD)." (PMID 36421473, 2022). "Charged multivesicular body protein 2B (CHMP2B), a component of the endosomal sorting complex, causes vacuolisation, lysosomal mis-localisation and impaired autophagy in cultured cells and has been associated with frontotemporal dementia (FTD; FTD3) and ALS (ALS17)." (PMID 23539154, 2013). "Given the patient’s family history of frontotemporal dementia (FTD) in a maternal uncle, the genetic analysis was extended to include the most common genes associated with FTD (TARDBP, GRN, TBK1, CHMP2B, SQSTM1, UBQLN2, VCP and MAPT) but no additional variants of clinical significance were detected." (PMID 40659544, 2025). "In a recent MRI study of familiar frontotemporal dementia (FTD-3) prior to symptom onset, the authors found a significant decrease of CBF in temporal, occipital, and parietal regions of familial carriers of the CHMP2B mutation, compared to family members not carrying the mutation." (PMID 22783187, 2012).
frontotemporal dementia (continued). "In particular, mutations in the ESCRT-III protein charged multivesicular body protein 2b (CHMP2b), responsible for ILV scission through its recruitment of the membrane-severing AAA-ATPase Vps4, result in frontotemporal dementia (FTD) and amyotrophic lateral sclerosis." (PMID 40021219, 2025).
amyotrophic lateral sclerosis (23 papers, 2010 to 2025). Amyotrophic lateral sclerosis (ALS) is a neurodegenerative disease characterized by progressive muscular paralysis reflecting degeneration of motor neurons in the primary motor cortex, corticospinal tracts, brainstem and spinal cord. "Although the Hgstn/tn mice represent the first report linking ESCRT-0 to neuromuscular disease, mutations in the ESCRT-III component CHMP2B have been linked to amyotrophic lateral sclerosis, and patients with CHMP2B mutations exhibit phenotypes consistent with lower motor neuron disease." (PMID 26115514, 2015). "CHMP2B encodes an ESCRT-III protein, and its mutation has been associated with frontotemporal dementia linked to chromosome 3 (FTD3) and amyotrophic lateral sclerosis (ALS)." (PMID 34440370, 2021). "Mutations in multivesicular body protein 2B (CHMP2B), a component of the ESCRT-III complex, are linked to both frontotemporal dementia and amyotrophic lateral sclerosis." (PMID 26115514, 2015). "Interestingly, mutations in CHMP2B are also causal for the development of FTD and amyotrophic lateral sclerosis." (PMID 26373282, 2015). "Mutations of the CHMP2B, a gene encoding a subunit of the ESCRT-III protein, have been identified in some patients with front temporal dementia and amyotrophic lateral sclerosis, thus, suggesting that impaired ESCRT-III function can contribute to neurodegenerative disorders." (PMID 23144710, 2012). "Mutations in the charged multivesicular body protein 2B (CHMP2B) gene are of particular interest due to their association with FTD, Amyotrophic lateral sclerosis (ALS), and early-onset AD." (PMID 35741010, 2022).